DSG2 (desmoglein 2)
Diseases named in the same sentence as DSG2 in open-access papers (continued):
Sharing a sentence is not in itself a finding about the gene and the disease.
systemic sclerosis (5 papers, 2013 to 2023). A chronic disorder, possibly autoimmune, marked by excessive production of collagen which results in hardening and thickening of body tissues. "DSG2 has also been reported to regulate actin assembly through interaction with integrin-β8 to promote angiogenesis in systemic sclerosis microvascular endothelial cells, and to serve a pro-survival role in intestinal epithelial tissue." (PMID 38188287, 2023). "The precise role for DSG2 in systemic sclerosis and angiogenesis is still unclear, with recent evidence suggesting impaired actin assembly and correlation with integrin β8 complex formation." (PMID 27338829, 2016).
viral infection (5 papers, 2022 to 2026). "Western blotting analysis confirmed the expected effect of viral infection, as DSG2 protein level was reduced by ∼75% in cells infected with Ad‐shDsg2, already at low MOI." (PMID 39141822, 2025). "The DSG2-dependent infectivity of Ad5/3(S) could be affected at several stages of the virus infection process, including virus attachment, internalization, endosome release, intracellular trafficking to the nucleus, and import of the viral genome into the nucleus." (PMID 36360292, 2022). "It remains unclear whether HAdV-7 relies on both CD46 and desmoglein-2 (DSG2), whether these receptors act synergistically or independently, and how their interactions influence viral infection dynamics." (PMID 41989164, 2026).
autoimmune (4 papers, 2013 to 2023). "Therefore, in this study we investigated the roles of Dsg2 and Dsg3, the latter of which is known to be essential for keratinocyte adhesion based on its autoantibody-induced loss of function in the autoimmune blistering skin disease pemphigus vulgaris (PV)." (PMID 23326495, 2013). "Detailed mechanistic studies are required to reveal the link between autoimmunity to DSG2 and the long-term sequelae of SARS-CoV-2 infection." (PMID 37095599, 2023). "To further evaluate whether the observed DSG2 cleavage is specific for autoantibodies from AC patients, we tested whether autoantibodies causing the autoimmune blistering skin disease pemphigus vulgaris (PV), which are directed primarily against DSG3, also induce DSG2 cleavage." (PMID 37450050, 2023).
colitis (4 papers, 2019 to 2022). Inflammation of the colon. "Intestinal epithelial DSG2 knockout mice exhibit severe colitis from DSS treatment with increased intestinal permeability." (PMID 36010621, 2022). "DSG2 protein expression was detected by IHC in CC tissues and related pericarcinomatous tissues and colitis tissues." (PMID 33407183, 2021). "In DSS-colitis, Dsg2 was reduced in intestinal epithelium whereas Claudin2 was present along virtually all enterocytes." (PMID 34659262, 2021). "DSG2 was expressed mainly on cells’ membranes and partly in the cytoplasm and was low expression in CC compared with pericarcinomatous tissues and colitis tissues." (PMID 33407183, 2021). "Low DSG2 protein expression was observed in 56.22% (330/587) of CC samples, but only in 29.27% (12/41) colitis and 28.95% (33/114) of pericarcinomatous tissues." (PMID 33407183, 2021). "Shedding Dsg2 ectodomains by MMPs had been detected in the inflamed intestinal mucosa of mice with colitis and patients with ulcerative colitis." (PMID 30790141, 2019). "Intraperitoneal application of Dsg2-stablising Tandem peptide (TP) attenuated impaired IEB function, reduction of Dsg2 and increased Claudin2 in DSS-induced colitis in C57Bl/6 mice." (PMID 34659262, 2021). "Both the reduction of Dsg2 and the strong increase of Claudin2 were attenuated when TP was applied to animals with DSS-colitis." (PMID 34659262, 2021).
colon adenocarcinoma (4 papers, 2020 to 2023). "Since colon adenocarcinoma-derived Caco-2 and T84 cell lines are frequently used as in vitro models of functional epithelial barriers, we chose these two as models for analyzing the high-affinity DSG2 vectors." (PMID 36016457, 2022). "Upon knockdown of DSG2, DSC2 has been shown to be upregulated in colonic adenocarcinoma cell lines, and this might explain why we can still observe a positive adhesiotropic effect of EGFR or SRC inhibition upon Dsg2 knockdown." (PMID 36795511, 2023).
COVID-19 (4 papers, 2021 to 2023). A disease caused by infection with severe acute respiratory syndrome coronavirus 2. "Levels of autoantibody in sera from patients with severe COVID-19 were comparable to levels in patients with non-COVID-19-associated cardiac disease, potentially identifying DSG2 autoantibodies as a novel biomarker for cardiac damage." (PMID 37095599, 2023). "To determine if there was any association between severe COVID-19 and DSG2, we stained post-mortem cardiac tissue from patients who died from COVID-19 infection." (PMID 37095599, 2023). "In this study, we have found raised DSG2 protein and a higher frequency of DSG2 autoantibody production in patients with or following severe COVID-19." (PMID 37095599, 2023). "Staining of post-mortem cardiac tissue from individuals that died from COVID-19 with an anti-DSG2 antibody revealed disruption of the intercalated disc between cardiomyocytes that was consistent with separation of the DSG2 protein homodimer." (PMID 37095599, 2023). "In fact, a recent study identified a significant increase in anti-desmoglein-2 antibodies in people recently infected with COVID-19 compared to both a control group and patients with ARVC31." (PMID 36977772, 2023). "Given that cardiac involvement is an important and long-term consequence of COVID-19, and potential also within the spectrum of syndromes observed in ‘long-COVID’, we examined post-mortem heart tissue for DSG2 protein." (PMID 37095599, 2023). "We find raised levels of anti-DSG2 autoantibodies in sera from individuals following severe COVID-19." (PMID 37095599, 2023). "We found that DSG2 is localized to the intercalated discs, confirming previous studies, and importantly that these discs were only found to be widened in COVID-19 tissue samples as is seen in ARVC." (PMID 37095599, 2023). "In the non-COVID-19 post-mortem heart tissues DSG2 staining consistently presented as a single, distinct band." (PMID 37095599, 2023). "This confirmed DSG2 protein within the intercalated discs and disruption of the intercalated disc between cardiomyocytes in patients who died from COVID-19." (PMID 37095599, 2023). "All hearts from individuals who did (n = 8) or did not (n = 3) die from COVID-19 causes (n = 3) showed variable weak to strong staining of DSG2 corresponding to the site of the intercalated discs." (PMID 37095599, 2023). "We find increased levels of DSG2 protein in sera from acute COVID-19 patients." (PMID 37095599, 2023). "Furthermore, the detection of perturbed DSG2 staining in post-mortem human heart tissue from COVID-19 patients reveals structural changes of the cardiomyocyte intercalated discs which are rich in DSG2." (PMID 37095599, 2023). "Finally, we examine cardiac tissue, obtained post-mortem from patients who died from COVID-19, to explore the potential clinical relevance of the DSG2 autoantibodies and cardiac damage." (PMID 37095599, 2023). "Similarly, in this study, we find an increased rate of DSG2 autoantibodies, and that these persist to 6 months following an episode of severe COVID-19." (PMID 37095599, 2023). "In this study, we have measured desmosomal protein levels and investigated the presence of anti-DSG1, DSG2, and DSG3 antibodies in sera from patients with acute COVID-19 and in those who have recovered from COVID-19 infection." (PMID 37095599, 2023). "This suggests a potential relationship between DSG2 and SARS-CoV-2 infection in more severe COVID-19 presentations." (PMID 37095599, 2023). "No DSG2 staining was observed in the post-mortem lung tissue (n = 8) examined from COVID-19 patients." (PMID 37095599, 2023). "Furthermore, we find that DSG2 autoantibody levels are increased significantly in convalescent sera following severe COVID-19 but not in hospitalized patients recovering from influenza infection or healthy controls." (PMID 37095599, 2023).
multiple myeloma (4 papers, 2017 to 2023). "A similar phenomenon was found in patients with multiple myeloma, in which the up-regulated DSG2 on the surface of neoplastic plasma cells was associated with a striking reduction in progression-free survival and overall survival." (PMID 36016457, 2022). "Finally, given that the proteasome inhibitor bortezomib is a frontline therapy for myeloma, we examined whether loss of DSG2 could render the cells more susceptible to killing by this drug." (PMID 34245117, 2022). "More recently, we have also demonstrated that DSG2 facilitates cancer cell adhesion in multiple myeloma." (PMID 38188287, 2023). "This study suggests that desmoglein‐2 (DSG2) is a novel cell surface adhesion molecule expressed by neoplastic plasma cells of patients with multiple myeloma." (PMID 34245117, 2022). "Therefore, DSG2 is also suggested as an independent predictor of poor prognosis for patients with multiple myeloma." (PMID 36016457, 2022). "DSG2 is a readily measurable and clinically useful prognostic biomarker that may prove to be a novel target to combat myeloma progression and improve patient outcomes." (PMID 34245117, 2022). "Moreover, DSG2 directly contributes to the adhesive interactions between multiple myeloma plasma cells and bone marrow endothelial cells, which may support the dissemination of tumor cells to new sites within the bone marrow." (PMID 36016457, 2022).
breast tumor (3 papers, 2023 to 2025). "When DSG2 was knocked down, the inhibitory effect of hirudin on desmosome connection, adhesion and aggregation of breast tumor cells was abolished." (PMID 41381723, 2025). "This action disrupts DSG2-mediated desmosome junctions and weakens cell adhesion, thereby inhibiting the formation of CTC clusters in breast tumor cells and reducing lung metastasis." (PMID 41381723, 2025).
channelopathy (3 papers, 2021 to 2024). Channelopathies are a group of diseases caused by the dysfunction of ion channel subunits or their interacting proteins. "The variants included three channelopathy-associated genes (RYR2, CACNA1C, and ANK2), three HCM- or DCM-associated genes (MYH7, LDB3, and PRKAG2), five ACM-related genes (PKP2, JUP, DSG2, DSP, and TMEM43), and two cardiac transcription factor genes (TBX5 and GATA4)." (PMID 39272661, 2024).
esophageal squamous cell carcinoma (3 papers, 2022 to 2023). Esophageal squamous cell carcinoma (ESCC) is a type of esophageal carcinoma (EC) that can affect any part of the esophagus, but is usually located in the upper or middle third. "Here, we aimed to evaluate the diagnostic potential of serum desmoglein-2 (DSG2) in patients with esophageal squamous cell carcinoma (ESCC) and esophagogastric junction adenocarcinoma (EJA)." (PMID 35521959, 2022).
familial hypercholesterolemia (3 papers, 2018 to 2025). An inheritable form of hyperlipidemia, in which there are excess lipids in the blood. "Four disease–associated genes in the proband presented VUS: APC, APOB, DSG2, and DSP, respectively associated with familial adenoma polyposis, homozygous familial hypercholesterolemia and hereditary cardiac disease." (PMID 30233642, 2018).
head and neck squamous cell carcinoma (3 papers, 2022 to 2024). A squamous cell carcinoma that arises from any of the following anatomic sites: lip and oral cavity, nasal cavity, paranasal sinuses, pharynx, larynx, and salivary glands. "My Mahoney (Thomas Jefferson University) discussed the role of the cadherin and cancer biomarker desmoglein 2 (Dsg2) in head and neck squamous cell carcinoma (HNSCC), especially in the context of therapy with immune checkpoint inhibitors (ICI)." (PMID 39811728, 2024). "Further, studies using enzyme-linked immunosorbent assay (ELISA) have confirmed that the high expression of DSG2 in serum from patients with head and neck squamous cell carcinoma (HNSCC) can serve as a potential biomarker." (PMID 35521959, 2022).
Myocardial fibrosis (3 papers, 2021 to 2025). "The study of a DSG2 knockout murine model of ACM revealed cardiac inflammation as a critical early event leading to myocardial fibrosis." (PMID 37288269, 2023). "It is worth noting that in our case, patients did not have myocardial fibrosis according to the cardiac MRI, which is atypical for patients with mutations in DSG2." (PMID 34202524, 2021).
Naxos disease (3 papers, 2008 to 2025). A recessively inherited condition with arrhythmogenic right ventricular dysplasia/cardiomyopathy (ARVD/C) and a cutaneous phenotype, characterized by peculiar wooly hair and palmoplantar keratoderma. "Both conditions are inherited in an autosomal recessive manner, with Naxos disease caused by DSG2 mutations and Carvajal syndrome caused by DSC2 mutations." (PMID 41426600, 2025).
pancreatic ductal adenocarcinoma (3 papers, 2022 to 2025). An infiltrating adenocarcinoma that arises from the epithelial cells of the pancreas. "We employed the pancreatic ductal adenocarcinoma cell line AsPC-1 bearing a KO of DSG2 and generated hepatocyte-specific Dsg2 and Dsc2 KO mouse models." (PMID 39107343, 2024). "Proteomics analysis of tissues from patients with pancreatic ductal adenocarcinoma identified DSG2 as among the top four candidate up-regulated proteins, and serum validation showed significant elevation of DSG2 levels in cancer patient samples." (PMID 35521959, 2022). "DSC2 has been well characterised in pancreatic ductal adenocarcinoma (PDAC); therefore, we focused this study on DSG2 in PCSCs." (PMID 40615400, 2025). "We applied the pancreatic ductal adenocarcinoma cell line AsPC-1 with and without a knockout (KO) of DSG2 and generated mouse lines with a hepatocyte-specific KO of the known interacting partners of DSG2 (DSG2 and desmocollin-2)." (PMID 39107343, 2024).
pemphigus foliaceus (3 papers, 2010 to 2022). Pemphigus foliaceous is a rare superficial pemphigus disease characterized by multiple, pruritic, scaly, crusted cutaneous erosions, with flaky circumscribed patches, localized mostly on the face, scalp, trunk and extremities, often presenting an erythematous base. "There was a correlation between anti-desmoglein 2 and anti-desmoglein 1 titers in pemphigus foliaceus (r = 0.1680; p = 0.0206)." (PMID 35058080, 2022). "Higher titers of anti-desmoglein 2 (optical density) resulted in pemphigus foliaceus and pemphigus vulgaris, when compared to controls (0.166; 0.180; 0.102; respectively; p < 0.0001)." (PMID 35058080, 2022). "In pemphigus foliaceus (PF), patients develop pathogenic autoantibodies that target Dsg1 and promote cell-cell disadhesion in the superficial epidermis, where Dsg1 is highly expressed, but which lacks Dsg3 and Dsg2." (PMID 20631906, 2010). "Internalization granules of desmoglein 1 and 3, but not of desmoglein 2, were observed in lesions of pemphigus foliaceus and pemphigus vulgaris, respectively." (PMID 35058080, 2022).
skin carcinoma (3 papers, 2016 to 2022). "Thus, our finding here that Dsg2 can modulate EGFR activation is a critical link that connects cell-cell adhesion to mitogenic signaling in skin cancer development." (PMID 26918609, 2016).
skin squamous cell carcinoma (3 papers, 2020). A carcinoma arising from the squamous cells of the epidermis. "Further study shows that overexpression of DSG2 in human skin squamous cell carcinoma cell line enhances EGFR activation and increases cell proliferation and migration through a c-Src and EGFR dependent manner." (PMID 32095325, 2020). "Studies showed that DSG2 was aberrantly expressed in many tumors, such as gastric cancer, skin squamous cell carcinomas (Kurzen, Munzing & Hartschuh, 2003) and melanoma." (PMID 32095325, 2020).
skin tumor (3 papers, 2014 to 2016). "Correspondingly, ectopic expression of Dsg2 in suprabasal keratinocytes causes hyperproliferation of the epidermis and development of skin tumors." (PMID 24558503, 2014). "Based on this evidence, we proposed to determine if Dsg2 and Hh signaling cooperate in skin tumor development." (PMID 25871385, 2015). "In summary, our results demonstrate that Dsg2 modulates Hh signaling, and this synergy may accelerate skin tumor development by different mechanisms." (PMID 25871385, 2015).
urinary tract infection (3 papers, 2014 to 2018). "In contrast adenoviruses from species B that cause ocular, respiratory or urinary tract infections utilize CD46 or desmoglein-2 (DSG-2) were described as cellular binding structures." (PMID 30194327, 2018). "Dsg2 was recently identified as the primary high-affinity receptor for serotype B adenoviruses, which cause respiratory and urinary tract infections." (PMID 24558503, 2014).
adenoma (2 papers, 2020). A neoplasm arising from the epithelium. "Strong correlation was found between Dsg-2 expression in adenomas and controls and between adenocarcinomas and controls." (PMID 33372636, 2020). "In adenomas, a distinct cytoplasmic presence of Dsg-2 was observed in addition to the usual membranous expression, with decreased expression in comparison with normal tissue." (PMID 33372636, 2020). "Regarding Dsg-2, the intensity of staining was strong (+++) in 100% of control samples, while in adenomas, 100% of specimens were stained moderately (++)." (PMID 33372636, 2020). "Very strong correlation was found in Dsg-2 staining expression between controls and adenomas (Kendall’s τ-c = 0.987, p < 0.001; Spearman’s ρ = 1, p < 0.001) and between controls and malignancies (Kendall’s τ-c = 0.995, p < 0.001; Spearman’s ρ = 0.950, p < 0.001)." (PMID 33372636, 2020). "Among the 10 adenoma tissues, positive expression of DSG1 was 8 (80.0%) and of DSG2 was 8 (80.0%), respectively." (PMID 32850288, 2020). "Furthermore, peritumoral tissues and adenoma with positive DSG1 and/or DSG2 expression exhibited moderate to severe dysplasia." (PMID 32850288, 2020). "Thus, the frequency of DSG1 and DSG2 proteins was calculated in EHCC tumour tissues, peritumoral tissues, adenoma tissues, and normal biliary tract tissues using immunohistochemical staining to evaluate whether the expression of DSG1 and/or DSG2 had any clinical or pathological significance in EHCC." (PMID 32850288, 2020). "Adenoma and peritumoral tissues with negative DSG1 and/or DSG2 protein expression exhibited atypical hyperplasia." (PMID 32850288, 2020).
adenovirus infection (2 papers, 2015 to 2020). "Caspase-8 cleavage produces a 50-kDa intracellular fragment during cell apoptosis induced by IFN-γ or TNF-α, while cellular ADAM-17 can produce an 80-kDa extracellular fragment of DSG-2 during adenovirus infection." (PMID 32457708, 2020). "The localization of their receptors coxsackievirus and adenovirus receptor, and desmoglein-2 in cell-cell junction complexes between polarized epithelial cells represents a major challenge for adenovirus infection from the apical surface." (PMID 25723153, 2015).
anaplastic thyroid cancer (2 papers, 2022 to 2024). "For instance, decreased Dsg2 expression indicated poor prognosis in gallbladder carcinoma, pancreatic cancer, melanoma, gastric cancer and anaplastic thyroid cancer." (PMID 38671389, 2024). "In anaplastic thyroid cancers, Lee demonstrated that DSG2 knockdown induced cell motility and invasiveness through the cMet/Src/Rac1 signaling axis and that targeting cMet inhibited DSG2 knockdown-induced distant metastasis in mouse xenografts." (PMID 35345582, 2022). "In addition, in anaplastic thyroid cancer Dsg2 depletion significantly increased metastatic potential through activation of c-Met which belonged to receptor tyrosine kinase (RTK) and also transmitted higher downstream p-AKT activity." (PMID 38671389, 2024).